MUC4 (mucin 4, cell surface associated)
Diseases named in the same sentence as MUC4 in open-access papers (continued):
Sharing a sentence is not in itself a finding about the gene and the disease.
pancreatic cancer (continued). "Indeed, it is now established that MUC4 is able to modulate gene expression through cell signaling activation as we observed a significant decrease in NF-κB activity in MUC4-KD PANC89 pancreatic cancer cells." (PMID 34944818, 2021). "We observed that both miR-210-3p and MUC4 expression levels are increased in pancreatic cancer." (PMID 34944818, 2021). "Furthermore, it was observed that MUC1 and MUC4 are involved in IL-17RB-mediated resistance to gemcitabine in pancreatic cancer cells." (PMID 33082357, 2020). "Collectively, these results suggest IL-17RB could enhance gemcitabine resistance through upregulation of MUC1 and MUC4 in pancreatic cancer cells." (PMID 33082357, 2020). "Previous studies have shown that cancer antigen 19-9 (CA19-9) and mucin 4 (MUC4) are upregulated in pancreatic cancer, and these may be the targets of our selected peptides." (PMID 32380649, 2020). "IL-17RB, MUC1, and MUC4 are mainly expressed on the surface membrane of pancreatic cancer cells." (PMID 33082357, 2020). "Furthermore, MUC4 induces nuclear translocation of β-catenin, promoting growth, metastasis and angiogenesis in pancreatic cancer." (PMID 31514468, 2019). "A report indicated that YY1 could suppress invasion and metastasis by downregulating MMP10 in a MUC4/ErbB2/p38/MEF2C-dependent manner in pancreatic cancer cells, suggesting MEF2C phosphorylation is required for MMP10 expression." (PMID 30836712, 2019). "The mucin 4 (MUC4) gene is one example of promoter hypomethylation in pancreatic cancer." (PMID 31379917, 2019). "Using SERS, researchers from Iowa State University, University of Nebraska Medical Center, University of Pittsburgh Medical Center, and University of Utah demonstrate the first ever detection of the potential pancreatic cancer marker MUC4 in cancer patient serum samples." (PMID 30569241, 2018). "Follow-up of pancreatic cyst patients who show MUC4 expression might reveal clues to early detection of pancreatic cancer." (PMID 34164227, 2018). "Therefore, we conducted this study to compare and contrast MUC4 expression in pancreatic cancer and pancreatic cysts from Egyptian patients diagnosed and treated at the Mansoura University Gastrointestinal Surgery Center." (PMID 34164227, 2018). "One study has demonstrated that multiplex detection of pancreatic biomarkers CA19-9, MMP7, and MUC4 in sera samples were of high sensitivity, which may act as the critical biomarker in diagnosis of pancreatic cancer." (PMID 30428899, 2018). "Our results demonstrate: 1) NIDO, AMOP, and vWD domain or their synergy play significant roles on MUC4/Y-mediated malignant function of pancreatic cancer, downstream of molecule mechanisms, particularly MUC4/Y-triggered malignancy-related positive feedback loops, respectively." (PMID 28060749, 2017). "Altogether, these results demonstrate that MUC4/Y’s unique domains have significant roles in MUC4/Y-mediated malignant function of pancreatic cancer, downstream of molecule mechanisms, particularly MUC4/Y-triggered malignancy-related positive feedback loops, respectively." (PMID 28060749, 2017). "Importantly, the present study is the first to demonstrate that NIDO, AMOP, and vWD domain or their synergy play significant roles on MUC4/Y (MUC4)- triggered malignancy-related positive feedback loops of pancreatic cancer to a variable extent." (PMID 28060749, 2017). "MUC4 mucin is well known as an important potential target to overcome pancreatic cancer." (PMID 28060749, 2017). "Thus, finding paths to break the synergy of three unique domains (NAV) will be helpful to weaken capabilities of pancreatic cancer metastasis, specially to the patients with MUC4 positive expression." (PMID 28060749, 2017). "Similarly, MUC4 expression is increased in colon adenocarcinoma samples and is a proposed marker of aggressive pancreatic cancer." (PMID 27483328, 2016). "In a pancreatic cancer cell line, hypoxia induced an increase in expression of MUC4 mRNA." (PMID 27283771, 2016).
pancreatic cancer (continued). "Furthermore, it is possible that β-catenin acts as a molecular toggle, with high levels (as seen in CRC) repressing MUC4 and low to moderate levels (as seen in pancreatic cancer) promoting MUC4 transcription via a differential recruitment of co-factors." (PMID 27551331, 2016). "Besides, nicotine/cigarette smoke promotes metastasis of pancreatic cancer through α7-nAChR mediated Mucin-4 (MUC4) upregulation." (PMID 26981122, 2016). "Notably, silencing of EGFR family member in pancreatic cancer cells decreased MUC4 expression through reduced phospho-STAT1." (PMID 25686822, 2015). "Interestingly, we observed increased co-localization of Muc4/Her3 in various stages (10th, 20th and 25th weeks) of pancreatic cancer progression in mice tumor tissues than Muc4/Her2 expression." (PMID 26035354, 2015). "Furthermore, MUC4 mucin overexpression correlates with its capacity to potentiate tumor invasion and metastasis in pancreatic cancer." (PMID 25686822, 2015). "Our finding suggests that HER3 strongly interacts with MUC4 in HER2 knockdown pancreatic cancer cells as demonstrated by reciprocal immunoprecipitation assay, which suggests that HER3/MUC4 association is essential for HER2 low pancreatic cancer cells." (PMID 26035354, 2015). "Besides, we and others have demonstrated de novo expression of MUC4 in ~70-90% of pancreatic cancer patients and its stabilizing effects on HER2 downstream signaling in pancreatic cancer." (PMID 25686822, 2015). "Furthermore, earlier studies from our group have shown that MUC4 enhances invasion and metastasis of pancreatic cancer." (PMID 25686822, 2015). "In addition, we also showed that MUC4 induced the apoptosis of antigen-specific cytotoxic T lymphocytes and promoted tumor immune escape in pancreatic cancer." (PMID 26393880, 2015). "Hence, these results imply that pan-EGFR inhibitor inhibits phospho-STAT1 mediated response to regulate MUC4 expression in pancreatic cancer cells, thereby abrogating tumor advancement towards metastasis." (PMID 25686822, 2015). "MUC4 is differentially expressed at various stages of pancreatic cancer." (PMID 26035354, 2015). "Moreover, MUC4 transcriptional upregulation was found to be activated by EGF mediated signaling response along with activation of intracellular tyrosine kinase in pancreatic cancer cells." (PMID 25686822, 2015). "Our study provides a strong evidence of profound effects of irreversible pan-EGFR inhibitors (TKIs) in down regulating MUC4 mucin through its effect on the EGFR family proteins resulting in decreased pancreatic cancer cell proliferation, survival and migration." (PMID 25686822, 2015). "Based on our recent work, we propose miR-219-1-3p as a good tumor-suppressor candidate to inhibit MUC4 expression, MUC4-mediated downstream signaling pathways, and MUC4-independent cellular tumor suppressor mechanisms highlighting the therapeutic potential of this miRNA in pancreatic cancer." (PMID 26682251, 2015). "Interestingly, our previous study has shown that the MUC4 promoter has STAT1 binding sites and serine phosphorylation of STAT1 (ser727) regulates MUC4 expression in pancreatic cancer cells." (PMID 25686822, 2015). "Thus, treatment with erlotinib appears to be ineffective in controlling MUC4 mucin protein in pancreatic cancer." (PMID 25686822, 2015). "We believe that the early miR-219-1-3p repression and the resulting increased expression of the transmembrane mucin MUC4 may represent two key events that favor pancreatic tumor progression." (PMID 26682251, 2015). "In our present study, analyses of the DNA methylation status of MUC1, MUC2 and MUC4 in pancreatic juices were useful for differential diagnosis of human pancreatic neoplasms i.e. PDAC, intestinal-type IPMN and gastric-type IPMN, with high specificity and sensitivity." (PMID 24714692, 2014).
pancreatic cancer (continued). "The positive correlation between MUC4/Y and MUC4 expression levels in PDAC clinical samples also suggests that MUC4/Y might play similar roles as MUC4 in the malignant progression of pancreatic cancer." (PMID 25367394, 2014). "So we speculated that MUC4/Y might be involved in malignant progression similarly to FL-MUC4, and as a research model of MUC4 in pancreatic cancer." (PMID 25367394, 2014). "The pancreatic cancer cell line BXPC-3 is MUC4 positive-expression as positive control." (PMID 25367394, 2014). "Analyses of the DNA methylation status of MUC1, MUC2 and MUC4 were useful for differential diagnosis of human pancreatic neoplasms, with specificity and sensitivity of 87% and 80% for PDAC; 100% and 88% for intestinal-type IPMN; and 88% and 77% for gastric-type IPMN, respectively." (PMID 24714692, 2014). "Moreover, biocomputational tools allowed to demonstrate that among the most differentially expressed genes in pancreatic cancer were Mesothelin, Muc4, Muc5A/C, Kallikrein 10, Transglutaminase 2, Fascin, TMPRSS3 and Stratifin." (PMID 25275504, 2014). "MUC4 plays important roles in the malignant progression of human pancreatic cancer." (PMID 25367394, 2014). "Previous studies showed that MUC4 and ErbB2 might interact physically and transduce signals intracellularly, thus promoting the migratory and metastatic potential of pancreatic cancer cells." (PMID 24884523, 2014). "In the present work, we undertook to identify the intracellular signalling pathways under the control of either ErbB2 or MUC4 in the same cellular model of pancreatic cancer to test this hypothesis." (PMID 22393391, 2012). "Given this background, experiments were conducted to assess whether MUC4 plays a role in mediating the proliferation as well as invasion of pancreatic cancer cells." (PMID 22537161, 2012). "MUC4 was also found to be necessary for the nicotine-mediated invasion of pancreatic cancer cells, suggesting that induction of MUC4 by nicotine and other agents might contribute to the genesis and progression of pancreatic cancer." (PMID 22537161, 2012). "IFN-γ upregulates MUC4 in pancreatic cancer cells through STAT1 expression." (PMID 22479354, 2012). "MUC4, a transmembrane mucin is overexpressed in pancreatic tumors, while remaining undetectable in the normal pancreas, thus indicating a potential role in pancreatic cancer pathogenesis." (PMID 22537161, 2012). "Boyden chamber assays were carried out to assess whether MUC4 play a role in nicotine-mediated invasion of pancreatic cancer cells." (PMID 22537161, 2012). "We show that human MUC4 and ErbB2 do physically interact in pancreatic cancer cells and that inhibition of expression of each membrane partners does not impair the same signalling pathways (inhibition of MUC4 expression affects the JNK pathway whereas that of ErbB2 alters the MAPK pathway)." (PMID 22393391, 2012). "Given that nicotine stimulates the binding of E2F1 to a variety of promoters, and since STAT1 is known to induce MUC4, we decided to examine whether these factors mediate the induction of MUC4 in pancreatic cancer cells." (PMID 22537161, 2012). "It appears that targeting these signaling pathways might inhibit the expression of MUC4 and prevent the proliferation and invasion of pancreatic cancer cells." (PMID 22537161, 2012). "Further, our recent studies have demonstrated that MUC4 results in oncogenic transformation of mouse fibroblasts, contributes to the drug-resistance of pancreatic cancer cells by activating anti-apoptotic pathways, and is involved in the epithelial-to-mesenchymal transition in ovarian cancer cells." (PMID 21886786, 2011). "Three anti MUC4α-N-Ter and one anti-MUC4α-C-Ter antibodies were characterized by several inmmunoassays including enzyme-linked immunosorbent assay (ELISA), immunoblotting, immunofluorescene, flow cytometry and immunoprecipitation using MUC4 expressing human pancreatic cancer cell lines." (PMID 21886786, 2011).
pancreatic cancer (continued). "Pancreatic cancer cells have been the major model for MUC4 regulation." (PMID 24281201, 2010). "In the future, it will be of interest to examine the effect of gemcitabine treatment on MUC4-expressing and non-expressing pancreatic cancer cell lines in vivo to support the pathogenic relevance of MUC4 with the acquisition of resistance to chemotherapeutics." (PMID 19738614, 2009). "Indeed, MUC4 forms a protein complex with the ErbB-2 receptor in human pancreatic cancer cells and modulates its downstream signalling." (PMID 19672266, 2009). "We showed that MUC4 protects CD18/HPAF pancreatic cancer cells from gemcitabine-induced apoptosis." (PMID 19738614, 2009). "To determine whether MUC4 exerts its anti-apoptotic function in pancreatic cancer cells through HER2, we examined the expression and activation of HER2 and its downstream signalling proteins." (PMID 19738614, 2009). "In addition, studies by overexpression and down-regulation of MUC4 in various pancreatic cancer cells showed its involvement in the development and progression of pancreatic cancer." (PMID 19738614, 2009). "Another question to address is whether the decrease of MUC1 and MUC4 expression could contribute to the AP-2α-induced sensitisation of pancreatic cancer cells to gemcitabine." (PMID 19672266, 2009). "Similarly, MUC4 has been shown to be involved in the growth and metastasis of pancreatic cancer cells." (PMID 18665193, 2008). "MUC4 also interacts with ErbB2, a growth factor receptor, stabilizes it at the cell surface and hence has an important function in modulating ErbB2-mediated oncogenic signaling in pancreatic cancer cells." (PMID 18781152, 2008). "CD18/HPAF is a MUC4-expressing pancreatic cancer cell line used as a positive control." (PMID 18665193, 2008). "However, in our MUC4 knockdown cell line model, we showed that endogenous overexpression of MUC4 is preventing apoptosis of the CD18/HPAF pancreatic cancer cells after 48–72 h serum starvation." (PMID 17595659, 2007). "In addition, an inhibition of MUC4 mucin in pancreatic cancer cells, using an antisense strategy, diminished in vitro and in vivo growth of cancer cells." (PMID 17595659, 2007). "Hence, MUC4 can be a useful target in the development of novel therapeutic strategies for the treatment of pancreatic cancer." (PMID 17595659, 2007). "The number of cells migrated to the lower surface of the porous membrane under chemoattractive stimulus of FBS in the lower chamber was approximately twofold greater in both mini-MUC4-expressing pancreatic cancer cells in comparison with control transfected cells." (PMID 17595659, 2007). "TGF-β2 mediates the expression of MUC-4 in retinoic acid treated pancreatic cancer cells." (PMID 18157915, 2007). "The MUC4 mucin exhibits a pancreatic tumour-associated expression, with no detectable expression in a normal pancreas." (PMID 14760381, 2004). "In addition to HER2, MUC4 also interacts with HER3, which activates PI3K-ERK and focal adhesion kinase (FAK)-associated pathways, resulting in proliferation, metastasis, and angiogenesis in pancreatic cancer cells." (PMID 40699805, 2025). "MUC1 and MUC4 are reported to be involved in stemness which confers drug resistance in cancer cells, implicating that overexpression of IL-17RB may lead to enhancement of chemotherapy resistance through upregulation of these genes in pancreatic cancer cells." (PMID 33082357, 2020). "Importantly, MUC1 and MUC4 modulate chemoresistance of pancreatic cancer cell lines in vitro." (PMID 32707920, 2020). "Furthermore, MUC4 suppression in pancreatic cancer induces a change in the phenotype of cells, reducing the expression of mesenchymal cell-specific markers such as N-cadherin and vimentin and upregulating the expression of epithelial-specific markers such as cytokeratin-18, E-cadherin and occludin." (PMID 31514468, 2019).
pancreatic cancer (continued). "Chronic pancreatitis could impose higher risk for pancreatic cancer but studies that compared MUC4 expression in pancreatic cancer and chronic pancreatitis showed MUC4 expression in 91% of pancreatic cancer but not in chronic pancreatitis tissues." (PMID 34164227, 2018). "The gene MUC4 (Human mucin) was reported to be highly polymorphic, harboring numerous TR and presenting a VNTR polymorphism, which might contribute to the tumorigenicity in pancreatic cancer cells." (PMID 29770143, 2018). "Thus MUC4 is an important potential target to overcome pancreatic cancer." (PMID 28060749, 2017). "Consequently, MUC4 could drive cancer progression by engaging HER3 oncogenic signaling in HER2 low pancreatic cancer cells." (PMID 26035354, 2015). "Interestingly, erlotinib was unable to attenuate MUC4 protein level in pancreatic cancer cells which could be possibly due to the unaltered phosphorylation status of STAT1 (Ser 727)." (PMID 25686822, 2015). "Thus, canertinib and afatinib could involve either independently or MUC4 dependent regulation of pancreatic cancer cell growth and cell cycle alteration." (PMID 25686822, 2015). "Thus, the indirect pharmacological inhibition of MUC4 via canertinib or afatinib could result in developing pan-EGFR inhibitors as a molecular therapeutic agent against advanced pancreatic cancer." (PMID 25686822, 2015). "More importantly, it may be as a research function model of MUC4 in pancreatic cancer." (PMID 25367394, 2014). "Additionally, this study reveals the complexity involved in the regulation of MUC4 promoter and shows that this process may involve many signaling pathways and transcription factors that might mediate the over expression of MUC4 in pancreatic cancer." (PMID 22537161, 2012). "Thus intra-tumoral injections of the MUC4 oncotropic virus appeared to be a very specific way to perform gene delivery in pancreatic tumors by contrast to a broad tropism virus, which transduced normal pancreatic cells and reached tissues distant from the tumor and the injection site." (PMID 23088623, 2012). "Interestingly however, CLDN18 and MUC4 achieved the best results in terms of efficiency and specificity in vitro and could be suitable for specific gene transfer in pancreatic tumor cells." (PMID 23088623, 2012). "In our study, proliferation rate was not affected, although invasive and adhesive activities of SW1990 after MUC5AC inhibition were decreased markedly, suggesting that MUC5AC, similarly to MUC1 or MUC4, might have potential to accelerate progression of pancreatic cancer." (PMID 20492722, 2010). "Mucin 4 (MUC4) is membrane-bound, has a high expression in pancreatic cancer, and is involved in pathobiology and aggressiveness." (PMID 40563681, 2025). "Xenograft tissue staining showed the expression of markers found in some types of pancreatic cancers (ECAD, MUC2 and MUC4), as well as of the pan-cancer cytokeratin CK18, to various degrees." (PMID 39123450, 2024). "The present study describes the bright and selective labeling of pancreatic cancer in orthotopic mouse models implanted with the human pancreatic cancer cell lines SW1990 and CD18/HPAF using fluorescent MUC4 antibodies." (PMID 39458160, 2024). "Meanwhile, in pancreatic cancer cells and tumor tissue, there is a positive correlation between the expression of IL-17RB and the expression of MUC1 and MUC4." (PMID 37686343, 2023). "The meta-analysis demonstrated that the overall expression level of mucin and the expression levels of MUC4 and MUC16 were important prognostic predictors for pancreatic cancer patients." (PMID 35709153, 2022). "This study analyzed the relationship between the expression level of the mucin family and its subtypes (MUC1, MUC4, MUC5, MUC16) and the overall survival of patients with pancreatic cancer." (PMID 35709153, 2022).